MET (MET proto-oncogene, receptor tyrosine kinase)
Diseases named in the same sentence as MET in open-access papers (continued):
Sharing a sentence is not in itself a finding about the gene and the disease.
breast carcinoma (continued). "From a prognosis standpoint, higher levels of c-MET and phospho-c-MET in breast cancers correlate with worse prognosis." (PMID 40361420, 2025). "First, CCR2-KO or Merestinib treatment alone reduced the growth and survival of mammary carcinomas and inhibited M2 macrophage recruitment, indicating disruptions to CCL2 and HGF signaling with inhibition of CCR2 or MET." (PMID 40736024, 2025). "OC demonstrated antiproliferative, apoptotic, anti-angiogenic, antimigratory, anti-invasive, and antimetastatic effects, mainly on breast cancer, by targeting ERα, HER2, EGFR, and c-MET." (PMID 40002421, 2025). "OC also plays a role in suppressing EMT and inhibiting the activation of important targets in breast cancer therapy such as EGFR, HER2, and c-MET." (PMID 40002421, 2025). "HGF secreted by CAFs activates MET signaling, enhancing the colony-forming ability of cancer cells, and the use of HGF neutralizing antibodies can effectively reduce CAF-mediated breast cancer proliferation and invasion." (PMID 40890855, 2025). "MET has been found to co-express and/or crosstalk with members of the EGFR family, such as HER2, in breast cancer, leading to oncogenesis and drug resistance via activation of PI3K/Akt and Ras/MAPK pathways." (PMID 40560045, 2025). "In this study, we assessed the coexpression of MET and ESR genes and their impact on tumor features and treatment outcomes in breast cancer." (PMID 39742369, 2024). "Certain targets were enriched in specific cancer types as expected based on the clinical treatment landscape or tumor biology (eg, EGFR, MET, ROS1, MET, and ALK in NSCLC; or ERBB2, CDK4, CDK6, aromatase, and ER in breast cancer)." (PMID 37682776, 2024). "Studies have shown that c-MET levels are elevated in luminal B- and HER2-overexpressing breast cancers compared to luminal A-expressing and triple-negative breast cancers." (PMID 39769140, 2024). "Our findings revealed distinct coexpression patterns of MET/ESR1 and MET/ESR2, each correlating with specific clinicopathologic features and clinical outcomes, thereby enriching the prognostic landscape of breast cancer." (PMID 39742369, 2024). "This was demonstrated using an engineered heterodimerization system in which the rapamycin-derived drug AP21967 induced the dimerization of MET-FKBP and β1 integrin-FRB in breast cancer cells." (PMID 39769452, 2024). "The top five CTRP hits in rank order include ML239 (breast cancer stem cell inhibitor), Niclosamide (anti tapeworm drug), Tipifarnib (H-Ras inhibitor), CHIR-99021 (GSK-3α/β inhibitor), and Tivantinib (MET inhibitor)." (PMID 36672285, 2023). "TCGA dataset analysis revealed a statistically significant correlation in protein expression between c-MET and phospho-AKT as well as phospho-ERK (p<0.001), while breast cancer patients with high expression levels of c-MET/AKT and c-MET/ERK." (PMID 37924112, 2023). "A significant correlation was found between mRNA abundance of c-MET and EGFR in breast cancer patients, and the concurrent overexpression of these genes was associated with comparatively poorer overall survival outcomes (p<0.0001)." (PMID 37924112, 2023). "Because no studies have reported correlations between THEMIS2 and MET activity in breast cancer thus far, we assessed their clinical connection by examining THEMIS2 and p-MET protein levels in breast cancer tissue specimens." (PMID 34974522, 2022). "Future studies would involve in-depth isotope tracing studies on breast cancer cell lines and tissues to determine the contributions of glucose and glutamine to CCL2/CCR2- and MET-mediated metabolism during DCIS progression." (PMID 35405500, 2022). "FEN1-mediated DNMT3a up-regulation, released the suppression of its targeting MET and EGFR, and promoted breast cancer cell proliferation by activating PI3K/AKT and MAPK/ERK pathways in MCF-7cells." (PMID 35620052, 2022).
breast carcinoma (continued). "We further identified corresponding targeting genes of TNBC-specific super-enhancers, including FOXC1, MET and ANLN, whose function and clinical relevance in breast cancer have been well documented." (PMID 34718356, 2022). "In metastatic human breast cancer cell line MDA-MB-231, which highly expresses the HGF receptor MET and CDCP1, we show that CDCP1 knockdown attenuated HGF-induced MET activation, followed by suppression of lamellipodia formation and cell migration/invasion." (PMID 35085554, 2022). "Recent studies have concluded that ASCs assist breast cancer recurrence and progression via the HGF/c-MET pathway." (PMID 36077676, 2022). "However, whether c-MET is upregulated in the stroma of breast cancer is unclear." (PMID 36530465, 2022). "In breast cancer cell lines, for example, HGF/c-MET interaction has been demonstrated to preferentially increase adhesion to laminins, fibronectin, and vitronectin via a PI3K pathway." (PMID 35630066, 2022). "Overall, these data indicate that: CCL2 triggers interactions among CCR2, MET and SRC in breast cancer cells, and CCL2 regulates MET phosphorylation through CCR2- and SRC-dependent mechanisms." (PMID 35405500, 2022). "This work unveils a new link between MET and NMDAR in breast cancers and highlights a new role of glutamate receptor in the proinvasive response to HGF." (PMID 36139568, 2022). "We next sought to establish if TICs derived from human breast cancers were specifically dependent on FGFR1 and MET signalling." (PMID 33772015, 2021). "In breast cancer cell lines, activation of the HGF pathway via binding of HGF to its receptor c-MET can lead to increased cell survival, proliferation, and resistance to cancer inhibitors." (PMID 34344422, 2021). "There is a need for biomarkers to improve efficacy to target the c-MET/HGF signaling pathway, especially within breast cancer." (PMID 34344422, 2021). "Along with ESR-1; EGFR, MET, and VEGFR are located centrally in the network which indicates the role of proteins in the pathogenesis of breast cancer." (PMID 33057155, 2020). "In the subgroup analysis, c-MET was correlated to OS in the subgroups with patients older than 65 years at diagnosis, PR low-expressing tumors, luminal B-like HER2− breast cancer subtype, invasive ductal tumors, and histological grade II tumors." (PMID 32188473, 2020). "Here we have examined the effects of MET in a novel co-culture system comprising primary MOs and ER-/PR-/HER2+ breast cancer cells." (PMID 33108409, 2020). "In female breast cancer, HGF and c-MET have been identified as a predictor for worse outcomes and are associated with a high Ki-67 labeling index." (PMID 32188473, 2020). "The hepatocyte growth factor (HGF)/c-MET axis and the stromal cell-derived factor-1 (CXCL12)/C-X-C chemokine receptor type 4 (CXCR4) axis are prognostic in women with breast cancer." (PMID 32188473, 2020). "In female breast cancer, HGF/c-MET promotes cell proliferation, migration, and invasion by HGF binding-induced c-MET activation of the phosphoinositide 3-kinase/Akt pathway and the Erk/mitogen-activated protein kinase cascade." (PMID 32188473, 2020). "Correlation of ETS1 with MET and TGFBR2 was observed as well in breast cancer tissue using the TCGA breast cancer dataset." (PMID 30004628, 2018). "In human breast cancer, H19 lncRNA-derived miR675 targets c-Cbl and Cbl-b, E3 ubiquitin ligases which are known to degrade EGFR and c-MET thereby increases the stability of latter." (PMID 29455658, 2018). "The function of miRNAs-HGF/c-MET axis in several human cancers has also been explored, including NSCLC, renal cancer, breast cancer, bladder cancer, and other cancers." (PMID 30360560, 2018). "Overexpression of miR‐128‐3p reduced MET expression and abrogated HGF‐induced cell migration of invasive breast cancer cells." (PMID 30004628, 2018).
breast carcinoma (continued). "Matriptase was highly expressed in breast cancer cell lines and involved in cancer progression through activation of the HGF/MET signaling axis." (PMID 30469509, 2018). "Breast cancer is the most prevalent cancer among women, and AXL and MET are the key genes in the PI3K/AKT/mTOR pathway as critical elements in proliferation and invasion of cancer cells." (PMID 30386383, 2018). "In breast cancer, the HGF/MET pathway activates the bone microenvironment through the Wnt-β-catenin pathway, and has an important role in the plasticity of bone metastasis." (PMID 29890660, 2018). "Luminal breast cancer cell lines MCF‐7, T47D, and MDA‐MB‐453 as well as the luminal HER2+ breast cancer cell lines BT474 and SKBR‐3 had very little surface expression of MET." (PMID 30004628, 2018). "To this end, we bioinformatically searched for putative transcription factor binding sites in the MET promoter and combined this with an analysis of genes that are coexpressed with either TGFBR2 or MET in breast cancer cell lines." (PMID 30004628, 2018). "Higher C‐ets‐1 and lower miR‐128‐3p expression levels intensify MET signaling and thereby suggest TGFβ1 as a regulator of HGF‐mediated migration in MCF10A and breast cancer cells." (PMID 30004628, 2018). "High expression of c-Met (MET+) correlated with expression of CSC markers, ALDH1A1 (p < 0.001), ALDH1A3 (p < 0.001), and CD133 (p < 0.001) in breast cancers." (PMID 28966724, 2017). "We evaluated the applicability of the ASCO/CAP HER2 guideline criterion for breast cancer to assess the EGFR, HER2, c-MYC, and MET gene status." (PMID 28764718, 2017). "Transfection of miR-206 repressed c-MET/EGFR levels in ovarian, renal, colorectal, and breast carcinoma cells." (PMID 29291022, 2017). "We evaluated EGFR, HER2, c-MYC, and MET gene status by determining the degree of amplification, GCN gain and the 2013 ASCO/CAP HER2 testing guideline criterion for breast cancer." (PMID 28764718, 2017). "In breast cancer, activation of HGF/MET/PI3K pathway drives tumor formation, metastasis, and drug resistance because of the crosstalk between MET and other oncogenic pathways." (PMID 26716644, 2016). "In the metastatic setting, increased MET copy numbers correlate with trastuzumab therapy failure in ERBB2-positive breast cancer and clinical trials with anti-MET therapy in advanced breast cancer are ongoing." (PMID 27576528, 2016). "A variety of genes, including PIK3CA, PTEN, TOP2A and MET are candidate markers for prognosis and response to treatment in ERBB2-positive breast cancer." (PMID 27576528, 2016). "A substantial increase in HGF and/or MET expression levels as a consequence of EGFR inhibition was shown to be responsible for the bypass of RTK inhibition in adult glioblastoma and breast cancer." (PMID 26496080, 2015). "A potential mechanism of tumor resistance against RTK inhibitors was found in non small-cell lung cancer (NSCLC) and HER2-positive breast cancer, where tumors became resistant to EGFR inhibition as a consequence of MET gene amplification." (PMID 26496080, 2015). "Microarray analysis in breast cancer cells revealed that knockdown of MTDH led to decreased expression of chemoresistance genes ALDH3A1, MET, HSP90, and HMOX1 and increased expression of proapoptotic genes BNIP3 and TRAIL." (PMID 25993398, 2015). "At high concentrations, NK1 was found to induce proliferation in a breast cancer epithelial cell line and in BALB/MK cells, MCF-10A cells, and in BaF3 cells expressing MET, albeit at a lower level than HGF." (PMID 28548073, 2014). "We have previously shown the involvement of the receptor tyrosine kinase MET and its ligand HGF (also known as scatter factor, HGF/SF) in tumor-bone interaction contributing to human breast cancer bone metastases." (PMID 24260160, 2013). "Compared to female breast cancer, IGF1-R and carbonic anhydrase 12 (CAXII) were more frequently and CD44v6, MET and FGFR2 less frequently expressed in male breast cancer." (PMID 23308200, 2013).
breast carcinoma (continued). "In conclusion, we found that expression of individual growth factor receptors (IGF1-R, FGFR2, and MET) and CD44v6, CAXII in male breast cancer is different compared to female breast cancer." (PMID 23308200, 2013). "The expression rates of HER2 and EGFR in male breast cancer were comparable with recent findings, but other data for IGF1-R and MET in the male breast cancer literature are unavailable." (PMID 23308200, 2013). "In our study population of 133 cases of male breast cancer, we found 4 cases (3.0%) expressing HER2, 15 cases (11.4%) EGFR, 6 cases (4.5%) MET, 16 cases (12.1%) FGFR2, and 50 cases (38.5%) IGF1-R." (PMID 23308200, 2013). "Further evaluation of human breast cancer tissues determined that MET overexpression was highly correlated with ER–/ERBB2– and basal-like breast cancers." (PMID 21049054, 2010). "Despite the limited number of studies evaluating the efficacy of TAS-115 on various cancer types, no research has specifically investigated its effects on c-MET/HGF-mediated breast cancer progression and metastasis, either alone or in combination with DOXO." (PMID 41289612, 2025). "Given the cooperative effects between CCL2 and HGF on breast cancer cells, we hypothesized that targeting CCR2 or MET alone would inhibit DCIS progression more effectively than inhibiting CCR2 or MET alone." (PMID 40736024, 2025). "Understanding the specific mechanisms that regulate CCL2 and HGF expression are regulated in breast cancer may enable us to predict when CCR2 and MET signaling may be altered during breast cancer progression." (PMID 40736024, 2025). "In addition, CCL2 also synergetic with HGF/MET pathway to promote the progression and metabolic reprogramming of breast cancer, and the combination of CCR2 knockout and MET inhibitor meritinib can more effectively inhibit tumor growth and stromal response." (PMID 41341593, 2025). "Further, biochemical studies of breast cancer cell lines from various subtypes could be helpful in clarifying the mechanisms through which CCR2 and MET overexpression regulates CCL2 and HGF signaling." (PMID 40736024, 2025). "MET also co-signals with other RTKs, such as RON, also widely known as the macrophage stimulating 1 receptor (MST1R), which is overexpressed or constitutively active in more than 50% of human breast cancer cases." (PMID 40560045, 2025). "Thus, a positive correlation between STMN1, MET, and HGF expression and metastasis, responsiveness to taxane, and overall survival in prostate and breast cancer patients is based on total STMN1 expression within these tumors." (PMID 40723207, 2025). "Similarly, in breast cancers, it was also found that MET mutation or amplification promotes tumor metastasis into more diverse organs; the median number of organs involved for the group of tumors with non-amplified MET was 2, compared to 7 for the MET amplified group." (PMID 40361420, 2025). "Subsequently, DTP cells have been identified in various experimental models after targeted therapy, including additional EGFR‐mutant NSCLC cell lines, MET‐amplified gastric cancer, BRAF‐mutant melanoma, prostate cancer, colorectal cancer, and HER2‐positive breast cancer." (PMID 39184861, 2024). "Similarly, in MDA-MB-231 breast cancer cells, the CD151 interaction with MET triggers AKT activation, leading to branching networks in matrigel." (PMID 39769452, 2024). "c-MET overexpression was observed in 4.7% (17/358), 3.8% (4/104), 7.1% (7/98), and 13.6% (22/162) of the primary sites in HR+/HER2−, HR+/HER2+, HER2-enriched, and Triple-negative breast cancer samples, respectively." (PMID 38238761, 2024). "Due to the intriguing correlation observed between NMDAR and MET in neurons, our previous investigation aimed to establish a connection between NMDAR and the HGF–MET pathway in the context of non-neuron cells such as breast cancer cells." (PMID 38201232, 2023). "Currently known oncodrivers in breast cancer are EGFR, HER2, HER3, MET, and mucin-1 (MUC1)." (PMID 36900322, 2023).
breast carcinoma (continued). "This also revealed that the sex or gender-specific cancer's (such as ovarian and breast cancers that are common among females) survival percentage is not influenced by the deregulation of the MET gene." (PMID 37200850, 2023). "Furthermore, MET and EGFR are well‐known oncogenes that activate the PI3K/Akt pathway in breast cancer, so trastuzumab cannot completely mitigate this signaling." (PMID 37325934, 2023). "This is important as MET pathway, including MET receptor and its ligand, hepatocyte growth factor (HGF), has a key role in cancer cell migration and metastasis and is an established target of breast cancer therapy." (PMID 36690660, 2023). "FEN1 was reported to elevate the expression of DNMT3A and promote their interaction among FEN1/PCNA/DNMT3A and suppressed the expression of miR-200a-5p, leading to upregulation of miR-200a-5p targets, MET and EGFR, which contribute to enhancement of growth of breast cancer cells." (PMID 35620052, 2022). "However, we are generating large RNAseq data from MCF7, a breast cancer cell line harboring LINE1-MET fusion, to build a specific CNN to be integrated with our MET exon 14 skipping models, to improve their specificity." (PMID 33921709, 2021). "In fact, while Tyr acts on the β-catenin and TGF-β pathways in breast cancer, in the same cancer model OC modulates the HER2/MET pathway and reduces vimentin by significantly inhibiting the recurrence rate, which is what makes these compounds exploitable in post-surgery therapy." (PMID 33513799, 2021). "Therefore, although differences between male and female breast cancer become apparent, the crosstalk among predominant biologic pathways and their function in males is not well understood, including that of the HGF/c-MET signaling." (PMID 32188473, 2020). "The expression of MET and EGFR, both of which are coding genes of receptor tyrosine kinases, is positively correlated due to the regulation of microRNA in non-small-cell lung cancer and breast cancer." (PMID 33204717, 2020). "In addition, both MET and CDK6 amplification have been described to contribute to trastuzumab resistance in HER2-overexpressing breast cancer." (PMID 31803359, 2019). "So far, no or little relation between LINC01234 and MET has been known, but our method found the gene pair LINC01234_MET as the most significant prognostic gene pair for breast cancer." (PMID 31856825, 2019). "Similarly, well characterized kinases known for their relevance in breast cancer are observed, such as ERBB2, EPHA1, MET and TGFBR2." (PMID 29643987, 2018). "Based on previous studies on breast cancer reporting that CD44+ CSCs expressed also the oncogene c-MET, and its inhibition blocked bone metastases from breast cancer, we tested a selective c-MET inhibitor." (PMID 29461491, 2018). "In line with our findings for TGFBR2, we observed higher MET expression in nonluminal compared to luminal breast cancer cell lines as well as nonluminal‐like compared to luminal‐like breast tumors." (PMID 30004628, 2018). "To this end, we activated MET and TGFβ signaling pathways with HGF and TGFβ1, respectively, and tested their influence on TGFBR2 or MET expression in the model cell line MCF10A as well as in basal‐like breast cancer cell lines HS578T and HCC1143." (PMID 30004628, 2018). "As for the 51 breast cancer cell lines, MET was higher expressed in breast tumors lacking ER expression than in samples with ER expression." (PMID 30004628, 2018). "Protein expression analysis revealed higher MET expression in triple‐negative compared to luminal‐like breast tumors in a set of 801 breast cancer tissue samples." (PMID 30004628, 2018).